FYN (FYN proto-oncogene, Src family tyrosine kinase)
Diseases named in the same sentence as FYN in open-access papers (continued):
Sharing a sentence is not in itself a finding about the gene and the disease.
tumor (continued). "Combination therapy targeting FYN +IGF1 R and KDM4 +EGFR synergistically eliminates tumor in vivo." (PMID 40243589, 2025). "Thus, for MC inhibition in the context of IgE‐dependent allergic or KIT‐driven neoplastic diseases, co‐inhibition of LYN, FYN, and KIT would be an evident advantage." (PMID 39676406, 2025). "FYN is a non-receptor tyrosine kinase that induces epithelial–mesenchymal transition, inhibits anti-tumor immune responses, and promotes tumorigenesis and metastasis." (PMID 39795978, 2024). "qRT-PCR results showed that the expression levels of BMX and FYN in HCC tumour tissues were significantly lower than those in adjacent normal tissues." (PMID 36873244, 2023). "Again, in the tissue microarrays of HCC patients, we found that the expression level of FYN in tumor tissues was lower than that in the adjacent tissues in most HCC patients, and the lower the expression level of FYN was, the worse was the prognosis of the patients." (PMID 35397600, 2022). "In conclusion, our study aimed to identify hub genes involved in HCC by WGCNA of data from the TCGA database and concluded that three functional genes (TGFBR3, COLEC10, and FYN) are highly differentially expressed in tumor and nontumor tissues." (PMID 35397600, 2022). "Further analysis of the correlation of the expression level of the prognostic genes with age, gender, tumor stage and tumor grade of HCC patients showed that the expression of FYN, PPP1CC, RAC1, and SPP1 was significantly correlated with the tumor grade (P < 0.05)." (PMID 33850056, 2021). "The reason for this contradiction is that phosphorylation of certain loci on Src and FYN may inhibit downstream signal transduction, which explains why CD148 exhibits a tumor-promoting effect in some tumors." (PMID 32201537, 2020). "Cav encodes caveolae protein 1 (caveolin), a scaffolding protein that links integrin subunits to the tyrosine kinase FYN; it is a tumour suppressor gene candidate and a negative regulator of the Ras-p42/44 mitogen-activated kinase cascade." (PMID 25297811, 2014). "Studies have shown that PIKE-A activation of Akt binds to STAT3, stimulating FYN and inducing STAT3 phosphorylation, thereby enhancing G6PD transcription, activating PPP metabolism, promoting DNA and NADPH synthesis, and inhibiting ROS production, ultimately fostering tumor growth." (PMID 39624082, 2024). "This study integrated HCC scRNA-seq and RNA-seq data and developed a tumor classification signature (MPCD index) based on extensive bioinformatics analysis and machine learning algorithms, and found four prognostic genes for HCC, S100A9, FYN, LGALS3, and HMOX1." (PMID 39795978, 2024). "FYN, a nonreceptor tyrosine kinase that belongs to the Src family kinases, promotes the development and progression of tumours and is closely related to the prognosis of patients with various tumours." (PMID 36873244, 2023). "Interestingly, when we overexpressed FYN in HCC cells, it seemed that FYN may acted as a tumor suppressor gene since it suppressed the migration and invasion ability and the proliferation of Hep3B and Huh-7 cells." (PMID 35397600, 2022). "Given the role of many SFKs in immune signaling pathways, increased phosphorylation of SFKs, such as LCK, LYN, FYN, and FGR could be associated with immune cell activation, rather than tumor cell signaling." (PMID 36077757, 2022). "Finally, we explored the function of FYN in HCC cells and xenograft tumor models." (PMID 35397600, 2022). "We also detected somewhat puzzling hypermethylation and silencing of genes that would be predicted to be oncogenes, rather than tumor suppressors, such as SF3B1, LCK, FOXP1, and FYN." (PMID 39189258, 2024).
infection (6 papers, 2013 to 2024). The state of being infected such as from the introduction of a foreign agent such as serum, vaccine, antigenic substance or organism. "We have perturbed the concentrations of the signaling molecules, viz., ZAP70, LCK and FYN, which are responsible for stimulating the TCR signaling pathway upon infection." (PMID 24324645, 2013). "After infection, MP antigens stimulate and upregulate T cell surface molecules including CD3D, CD3E, CD3G, and CD8, followed by the upregulation of downstream molecules including CD3Z, FYN, LCK, ZAP70, GADS, P38, and ITK." (PMID 29967623, 2018).
cardiovascular disease (3 papers, 2017 to 2019). "Our data suggests that although FYN might be acting as a natural antioxidant to reduce ROS effects, this mechanism might not be enough to reduce the inflammation caused by space radiation which has the potential to increase risk of cardiovascular disease." (PMID 30717456, 2019). "Interestingly it is known that LCK, LYN, and FYN are part of the SRC-family kinases (SFKs) and have been associated with various aspects of cardiovascular disease." (PMID 30717456, 2019). "In addition, FYN and AKT1 are shown to be pivotal with angiogenic functions and the relation to cardiovascular disease." (PMID 30717456, 2019).
neurodevelopmental disorder (2 papers, 2022 to 2025). A behavioral and cognitive disorder with onset during the developmental period that involves impaired or aberrant development of intellectual, motor, or social functions. "In contrast, ULK3 and FYN, key regulators of neuronal development and potential therapeutic targets for neurodevelopmental disorders, were upregulated at the protein level." (PMID 40568166, 2025).
adenocarcinoma (1 paper, 2015). A common cancer characterized by the presence of malignant glandular cells. "In particular, FYN expression was approximately 4-fold higher in NEPC patient tissues compared with a standard adenocarcinoma." (PMID 26624980, 2015).
hematopoietic cancers (1 paper, 2024). "In 3 independent studies, ZAP70, FYN, GRAP2, ITK, and CD247 (encoding CD3ζ) were highly upregulated in patients with T-ALL compared with individuals acting as healthy controls or people with other hematopoietic cancers, similar to our murine study." (PMID 38618957, 2024). "Furthermore, we found that expression levels of ZAP70, FYN, GRAP2, ITK, and LCK as well as two further TCR pathway kinases, PLCG1 and LAT, were highest in human T-ALL cell lines compared with other hematopoietic cancer lines." (PMID 38618957, 2024).
psychiatric disorder (1 paper, 2016). A disorder characterized by behavioral and/or psychological abnormalities, often accompanied by physical symptoms. "It is noted that 7 genes, DAO, PRDX6, KCNN3, TCF7L2, RFX4, FYN, and B3GAT2 (yellow-colored nodes), relevant to psychiatric disorders are involved and interestingly these genes except B3GAT2 constitute a connected subgraph." (PMID 27510319, 2016).
FYN also shares sentences with these, for which no sentence is quoted: neurodegenerative disease (3 papers); oral cancer (3); Hypertension (2); memory impairment (2); mesothelioma (2); myocardial infarction (2); adult T cell leukemia (1); Alcohol (1); alcohol dependence (1); amyotrophic lateral sclerosis (1); Anxiety (1); asthma (1); bipolar disorder (1); brain cancer (1); celiac disease (1); clear cell renal cell carcinomas (1); coronary heart disease (1); Crohn disease (1); cutaneous T-cell lymphomas (1); diabetic nephropathy (1); Dyskinesia (1); dyslipidemia (1); endothelial dysfunction (1); esophageal cancer (1); frontotemporal lobar degeneration (1); hematological diseases (1); Hepatitis (1); Hodgkins lymphoma (1); inflammatory bowel disease (1); interstitial lung disease (1).
A further 21 diseases each share a sentence with FYN in 1 paper.